IL5 (interleukin 5)
Diseases named in the same sentence as IL5 in open-access papers (continued):
Sharing a sentence is not in itself a finding about the gene and the disease.
psoriasis vulgaris (1 paper, 2022). Plaque psoriasis is the most common presentation of psoriasis. "We also assessed the causal effects of psoriasis vulgaris risk on circulating cytokine concentrations, which found that increased risk of psoriasis vulgaris resulted in elevated circulating levels of IL-1ra, IL-5, and MIG." (PMID 35769988, 2022). "Out of these 11 cytokines, the causal effects of psoriasis vulgaris achieved consistently significant on IL-1ra, IL-5, and MIG in all the 3 MR methods." (PMID 35769988, 2022). "We consistently found that psoriasis vulgaris affects the circulating levels of IL-1ra, IL-5, and MIG, which are consistent with previous findings." (PMID 35769988, 2022).
psychological distress (1 paper, 2022). "In conclusion, we found that psychological distress was associated with the cytokines IL-2, IL-4, IL-5, IL-10, IL-12, TNF-α, and IFN-γ." (PMID 36405903, 2022). "However, psychological distress was significantly associated with the plasma cytokines IL-2, IL-4, IL-5, IL-10, IL-12, TNF-α and IFN-γ." (PMID 36405903, 2022).
Psychosis (1 paper, 2023). "Psychosis in amphetamine-dependent women during early cessation is associated with increases in IL-10, TNF-α, and IL-5 (the latter cytokine was not measurable in our research)." (PMID 37996407, 2023).
pulmonary embolism (1 paper, 2025). The obstruction of the pulmonary artery or one of its branches by an embolus, sometimes associated with infarction of the lung. "Although CV disease event rates were four times lower (power loss) in patients aged ≤60 years, potential protective effects were maintained (especially on mortality, and additionally for anti-IL5/IL5R use on pulmonary embolism)." (PMID 40823190, 2025).
purpura (1 paper, 2021). A small blood vessel hemorrhage into the skin and/or mucous membranes. "Our findings showed that presence of purpura was associated with increased CRP and IL-5, and high disease activity in EGPA." (PMID 32770271, 2021). "Multivariate linear regression analysis of CRP and IL-5 showed that only CRP was related to the presence of purpura (p = 0.0223, 95% confidence interval 0.022–0.21)." (PMID 32770271, 2021). "In the univariate analysis, presence of purpura was associated with increased CRP and IL-5, and high BVAS score." (PMID 32770271, 2021). "In this study, the presence of purpura was significantly associated with CRP, IL-5 and high BVAS score, suggesting that cutaneous lesions reflected high disease activity of EGPA." (PMID 32770271, 2021). "We have concluded that a cutaneous lesion like purpura is an important index indicating robust inflammation in connection with increased IL-5 and eventually high disease activity of EGPA." (PMID 32770271, 2021).
renal fibrosis (1 paper, 2025). A final common manifestation of a wide variety of chronic kidney diseases characterized by glomerulosclerosis and tubulointerstitial fibrosis. "Hypoxia‐inducible factor‐prolyl hydroxylase (HIF‐PHD) inhibitors alleviated renal fibrosis through reduced phosphorylation of p38MAPK in ILC2s; thus, M2 polarisation followed by IL‐4/IL‐5/IL‐13 production was decreased, suggesting the pathogenesis role of ILC2/cytokines/M2 in renal fibrosis." (PMID 40801800, 2025).
retinal diseases (1 paper, 2025). "However, there are no reports on the function of IL5 in retinal diseases, and thus further studies are needed to interpret the present results." (PMID 39825912, 2025).
scoliosis (1 paper, 2015). A congenital or acquired spinal deformity characterized by lateral curvature of the spine. "The presence of scoliosis was significantly associated with IL-4 (r = 0.424, P < 0.0001), IFN-γ (r = −0.458, P < 0.0001), IL-12p70 (r = −0.327, P = 0.0029), IL-4/IFN-γ ratio (r = 0.491, P < 0.0001), IL-5/IFN-γ ratio (r = 0.442, P = 0.0001), and IL-6/IFN-γ ratio (r = 0.429, P = 0.0001)." (PMID 26236424, 2015).
scrub typhus (1 paper, 2023). Scrub typhus is a rare dust mite-borne infectious disease caused by the Orientia tsutsugamushi bacterium and characterized clinically by an eruptive fever which is potentially serious. "Ot infection can also slightly increase serum IL-5, IL-9, IL-13, and GM-CSF levels; however, their roles in scrub typhus remain unclear." (PMID 38091346, 2023).
selenium deficiency (1 paper, 2020). A nutritional deficiency disease resulting from inadequate selenium levels in the body, which can lead to impaired function of selenoproteins essential for antioxidant defense and thyroid hormone metabolism. "As IL-10, IL-13, IL-4, and IL-5 are part of Th2 responses, selenium deficiency may have induced more Th2 responses than Th1 responses in the lungs of mice infected with influenza virus." (PMID 33207753, 2020). "Selenium deficiency decreased the mRNA expression of IFN-γ and IL-2, but increased the mRNA expression of IL-10, IL-13, IL-4, and IL-5 in the mediastinal lymph nodes." (PMID 33207753, 2020).
skin abscess (1 paper, 2023). "Although the skin abscess area resulting from S. pseudintermedius infection was significantly smaller than that caused by S. aureus in mice, the expression of cytokines interleukin-4 (IL-4) and interleukin-5 (IL-5) were significantly higher in the S. pseudintermedius-infected mice." (PMID 37183254, 2023).
staphylococcus aureus infection (1 paper, 2025). An infectious process in which the bacteria Staphylococcus aureus is present. "In models of Staphylococcus aureus infection, LF increases pro-inflammatory cytokine TNF-α levels while decreasing interleukin-5 (IL-5) and interleukin-10 (IL-10) levels, confirming that LF accelerates the inflammatory response of host organisms to the infection." (PMID 40003872, 2025).
syphilis (1 paper, 2017). A contagious bacterial infection caused by the spirochete Treponema pallidum. "We prospectively recruited all patients with a new diagnosis of syphilis and tested their plasma for IFNα, IFNγ, IL-1β, IL-12p40, IL-12p70, IP-10, MCP-1, MIP-1α, MIP-1β, IL-4, IL-5, IL-6, IL-7, IL-8, IL-10 and IL-17A at baseline pre-treatment and 6 months following therapy." (PMID 28143443, 2017).
systemic vasculitis (1 paper, 2022). "The indication of anti-IL-5 agent for these patients was solely due to MEE as these patients had no other symptoms/signs of active systemic vasculitis." (PMID 35933390, 2022).
tauopathy (1 paper, 2024). Neurodegenerative disorders involving deposition of abnormal tau protein isoforms (tau proteins) in neurons and glial cells in the brain. "At the individual cytokine level, several important pro-inflammatory and immune-activating cytokines that increased with aging and tauopathy included Interleukin 5 (IL-5) and Macrophage-Inflammatory Protein 2 (MIP-2α), but these effects were reduced with Nanoligomer treatment." (PMID 39068433, 2024).
thalassemia (1 paper, 2021). An inherited blood disorder characterized by a decreased synthesis of one of the polypeptide chains that form hemoglobin. "This is because it is believed that patients with thalassemia have increased plasma malondialdehyde and circulating non-transferrin bound iron (NTBI) relative to patients with SCD, and lower levels of some cytokines (interleukin 5 and interleukin 10) and γ-tocopherol." (PMID 34760898, 2021).
thymic carcinoma (1 paper, 2025). Thymic carcinoma (TC) is a type of thymic epithelial neoplasm characterized by a high malignant potential. "Serum IL-18 levels were elevated—particularly in thymic carcinoma—and correlated with higher concentrations of type 2 cytokines (IL-4, IL-5, IL-9, IL-13)." (PMID 41368637, 2025). "Unexpectedly, thymic carcinoma cases exhibited a distinct cytokine milieu skewed toward type 2 inflammation, with increased levels of IL-4, IL-5, IL-9, and IL-13." (PMID 41368637, 2025).
thymoma (1 paper, 2022). A neoplasm arising from the epithelial cells of the thymus. "As lymphocytes express TNF‐α‐receptors I and II while not expressing receptors for IL‐5 or VEGFA, we tested whether the mouse lymphocyte derived BW5147 thymoma reporter cell line is sensitive to high concentrations of rhTNF‐α." (PMID 34842342, 2022).
thyrotoxicosis (1 paper, 2023). A hypermetabolic syndrome caused by the elevation of thyroid hormone levels in the serum. "Elevated levels of IFNa2 at T0 and IL-5 at T2 were associated with the progression of thyrotoxicosis." (PMID 37629267, 2023).
toxic epidermal necrolysis (1 paper, 2025). Toxic epidermal necrolysis (TEN) is an acute and severe skin disease with clinical and histological features characterized by the destruction and detachment of the skin epithelium and mucous membranes. "Severe cutaneous adverse reactions, including DRESS, SJS, and toxic epidermal necrolysis (TEN), involve pathogenic mechanisms in which cytotoxic CD8+ T lymphocytes, as well as certain pro-inflammatory eosinophil promoting cytokines (such as IL-4, IL-5, IL-9, IL-13), play a role." (PMID 40869188, 2025).
Tracheomalacia (1 paper, 2019). "The expressions of IL-5, IL-6, and IL-10 in BALF of AVP were significantly higher than those of MPP and tracheomalacia patients (p-value: 0.016, <0.001, <0.001, respectively)." (PMID 31316955, 2019).
unstable angina (1 paper, 2016). "This speculative mechanism fits with the IL5 locus being associated with MI and unstable angina, typically resulting from plaque rupture, but not with IMT, which is indicative of vessel wall remodelling." (PMID 26821299, 2016).
vaginal disorder (1 paper, 2018). A non-neoplastic or neoplastic disorder that affects the vagina. "Since IL5 and IL13 are strongly influenced by the alteration of eubiotic conditions, regardless of the specific pathogens causing the alteration of vaginal milieu, they could be further studied as indirect markers of vaginal disorder." (PMID 29396486, 2018).
vascular dementia (1 paper, 2023). A degenerative vascular disorder affecting the brain. "The significantly increased serum levels of IL-4 and IL-5 in the MCI/AD group correspond with findings in a previous study that reported elevated IL-4, IL-5, IL-1β, TNF-α, IFN-γ, G-CSF, and MIF-1b levels in patients with vascular dementia." (PMID 37760836, 2023).
Vestibular schwannoma (1 paper, 2024). A vestibular schwannoma (also known as acoustic neuroma, acoustic neurinoma, or acoustic neurilemoma) is a benign, usually slow-growing tumor that develops from the VIIIth cranial nerve supplying the inner ear. "In addition, the levels of proinflammatory/proallergic cytokines (IL-4, IL-5, IL-10, and IL-13) were higher in the macula, ampulla, and endolymphatic sac dissected from patients with MD than in the specimens from patients with vestibular schwannoma." (PMID 38595846, 2024).
viral myocarditis (1 paper, 2020). Myocarditis that is caused by an infection with a viral agent. "Some results have suggested that As IV can reduce IL-4, IL-5, and IL-17 levels to inhibit asthmatic effects and improve cardiac functions in children with viral myocarditis by reducing the levels of IL-17, IL-21, and caspase-3." (PMID 32317974, 2020).
vitamin A deficiency (1 paper, 2012). Deficiency of vitamin A due to malnutrition, malabsorption, or dietary lack. "By quantitative real-time PCR analysis (qRT-PCR) of isolated liver lymphocytes, we found that vitamin A deficiency significantly reduced the expression of IL-4, IL-5, and IL-13 but not of IFNγ." (PMID 22927819, 2012).
xerostomia (1 paper, 2023). Dryness of the mouth resulting from reduced salivary secretion. "Among the inflammatory cytokines assessed - IL-6, TNF-α, IFN-γ, IL-10, IL-12p70, IL-1β, IL-8, IL-13, IL-2, IL-5, IL-7 and IL-17A, xerostomia correlated with lower levels of saliva IL-2 and TNF-α, and elevated levels of serum IL-12p70 and IL-10 (p < 0.05)." (PMID 36846089, 2023).
Zinc deficiency (1 paper, 2010). A deficiency of the essential metal Zinc; an essential cofactor for many enzymes. "Overall, zinc deficiency was associated with increased supernatant concentrations of TNF and IFN-γ (by 37% and 74%, respectively), and seemed associated with increased concentrations of IL-5 and IL-13." (PMID 20546583, 2010).
infection (536 papers, 1996 to 2026). The state of being infected such as from the introduction of a foreign agent such as serum, vaccine, antigenic substance or organism. "Mice deficient in Irf4 in CD11c+ cells secrete less IL-4, IL-5, and IL-13 both in the SI and colon after infection with the parasite Schistosoma mansoni, and a similar outcome is observed after infection with T. muris and Nippostrongylus brasiliensis." (PMID 41028655, 2025). "We found that adjuvanting QIV with AddaVax resulted in a type 2-skewed host response to infection, with hallmark type 2 cytokines IL-4, IL-5, and IL-13 present in the lung homogenates of the aQIV group at 5 days post-infection." (PMID 39975920, 2025). "Th2 cytokines (IL-4, IL-5 and IL-13) were only associated with infection intensity in the oldest age group aged 14–18 years of age." (PMID 39250522, 2024). "Eosinophils increased at 9 weeks, associated with an IL-5 boost and pre-treatment infection intensities." (PMID 39250522, 2024). "In another study, a lower Th1/Th2 ratio and higher cytokine response ratios of IL-5 and IL-13 were found to be significantly associated with an increased risk of infections during maintenance therapy in MM patients." (PMID 39559703, 2024). "While isolates induced several common immune host responses to infection, one B.1 isolate was unique in the promotion of eosinophil-associated proteins IL-5 and CCL11." (PMID 36992320, 2023). "IL-2, IL-5, IL-17F, IFNγ and TNFα inductions were positively associated with the infection status in the N-peptides restimulated cells (308%, 65%, 39%, 304% and 40% increase when infected, respectively, FDR < 0.1)." (PMID 35313592, 2022). "IL-5 is an important cytokine because it regulates eosinophils whose levels in humans are associated with resistance and is important at the onset of infection." (PMID 34239575, 2021). "These cause the production of the cytokines IL-4, IL-5, and IL-13, which in turn influence Immunoglobulin E (IgE) levels and eosinophilia, components of immune response associated with infection/re-infection resistance in schistosomiasis." (PMID 34185775, 2021). "Significant associations between SNVs on IL21R and infection with A. lumbricoides and levels of anti-Ascaris lumbricoides IgE and IgG4 and parasite antigen induced production of IL-5 and IL-10 by PBLs." (PMID 33692795, 2021). "This increase of the Treg pathway was associated with a concomitant increase of Th2 cytokines (IL-5 and IL-13), as observed in several other models of infection and inflammatory diseases." (PMID 32571430, 2020). "Infection also results in activation of ILC2s to express IL-5 which is almost totally ablated in the MIF-deficient animals, within an overall reduction of ILCS in the MLN." (PMID 31708913, 2019). "Considering that type-2 immunity has been associated with resistance to infection by gastrointestinal nematodes, we next analyzed the gene expression of classical Th2 cytokines IL-4, IL-5, IL-13." (PMID 31862904, 2019). "Experimentally infected cattle have increased IL-2 and IFN-γ production in the first 2 to 3 weeks postinfection, while our study suggests that the early stages of natural infection are associated with increased IL-4 production and IL-5 transcription." (PMID 28993458, 2018). "Mitogen-stimulated release of IL3 and IL5 were significantly associated with increased risk for subsequent infection during maintenance therapy." (PMID 29051761, 2017). "Systemic TH2 cytokines were positively associated to infection intensity only in the oldest age group (IL-4: r = 0.488, p = 0.008; IL-5: r = 0.400, p = 0.027; IL-13: r = 0.497, p = 0.007)." (PMID 25799270, 2015). "The induction of prototypical Th2 response with high IL-4, IL-5 and IL-13 secretion has long been considered to be the hallmark of active infection in human LF." (PMID 24498448, 2014).
infection (continued). "The absence of eosinophils led to significantly longer Mf survival during primary infection (P<0.01), further clarifying our previous work in IL-5 and eotaxin-1 deficient mice." (PMID 24626328, 2014). "To more directly assess the impact of NKT cell deficiency on IL-5 production by ILC2 during infection, we examined ILC2 IL-5 production in total lung cell suspensions from WT and CD1d-/- mice at 7 and 12 d.p.i. using our ex vivo ICS assay." (PMID 24068930, 2013). "For both infections, the time to peak IL-5 levels was significantly associated with the time to peak eosinophil number." (PMID 23556029, 2013). "IL-5 levels 24-hr post-treatment were significantly associated with increased eosinophil number at 9-wk post-treatment, as were pre-treatment infection intensities." (PMID 23556029, 2013). "Circulating IL-5 levels increased 24-hr post-treatment and were associated with pre-treatment infection intensity, SWA-IgE levels, eosinophil number, as well as 24-hr post-treatment eotaxin levels." (PMID 23556029, 2013). "This is consistent with what occurs in intact mice, where infection of infants increased the release of the pro-asthmatic Th2 cytokines IL-5 and IL-13, which was associated with increases in MSC numbers and AHR." (PMID 22870337, 2012). "Hosts who produce IFN-γ/IL-4/IL-5 in association with IL-10 present high levels of infection, proposing that the regulatory component is strongest to define the severity of pathology." (PMID 20544012, 2010). "A previous study in a S. mansoni endemic Ugandan fishing community suggested that high IL-5 levels are associated with low S. mansoni levels in older individuals since high levels coincided with the lowest infection levels." (PMID 18045464, 2007). "However, once Schistosoma eggs are produced at 5–6 weeks of infection, the host immune status dramatically shifts to a Th2 response, as shown by the increased production of Th2-associated cytokines IL-4, IL-5, IL-10, and IL-13." (PMID 35584107, 2022). "Moreover, two SNPs in the IL-5 and IL-13 genes, which appeared to be associated with infection susceptibility, had to be considered as likely due to chance, because both associations were no longer significant upon permutation testing." (PMID 34185775, 2021). "During the infection course, expression of IL-5 might be associated with compensatory mechanisms in response to hippocampal alteration in CARD9−/− mice." (PMID 34209576, 2021). "The decrease of eosinophil levels in PEC was associated with higher levels of CCL11, TSLP, and IL-5 in the peritoneum, suggesting that infected animals increase the levels of these cytokines and chemokine to promote eosinophil differentiation during infection." (PMID 33042162, 2020). "Abundance was negatively associated with type 2 (IL4, IL5, single and dual infections) and regulatory T cells (FoxP3, single infection), and positively related to the inflammatory response (Tbet, RORγT, dual and single infections)." (PMID 31871660, 2019). "For helminth infection in humans, the immune response during the early/acute phase of infection involves the induction of type 2-associated cytokines (IL-4, IL-5, IL-9, and IL-13) first by innate lymphocytes (ILC2) and later by effector antigen-specific polyfunctional CD4 T cells." (PMID 30416709, 2018). "Early IL-5 production after treatment-induced exposure to S. haematobium worm antigen is positively associated with antigen dose (infection intensity), IgE availability for arming of effector cells at time of treatment and subsequent eosinophil migration response (as indicated by eotaxin levels)." (PMID 23556029, 2013). "We found that, whilst increasing in number, the IL-4gfp+CD4+ Th2 cells became conditioned towards a functionally hypo-responsive phenotype as infection progressed denoted by a progressive loss in their intrinsic ability to produce the cytokines IL-4, IL-5 and IL-2." (PMID 23516361, 2013).